MIR938 (microRNA 938)
Synonyms: hsa-mir-938; MIRN938
Gene: MicroRNA gene on chromosome 10 (29,602,264 to 29,602,346, reverse strand). Ensembl gene ENSG00000216035.
Gene Ontology:
Biological process: miRNA-mediated post-transcriptional gene silencing
Cellular component: RISC complex
Diseases named in the same sentence as MIR938 in open-access papers:
MIR938 is named in the same sentence as 1 disease in open-access papers, as found by Europe PMC text mining. Sharing a sentence is not in itself a finding about the gene and the disease. The quoted sentences say what the papers report.
gastric cancer (2 papers, 2023). A primary or metastatic malignant neoplasm involving the stomach. "Another variant present in the MIR938 gene has been associated with decreased risk of gastric cancer." (PMID 36901860, 2023). "Current existing articles have shown that MIR938 polymorphisms are associated with many kinds of diseases, including intestinal-type gastric cancer (intestinal-type GC), colorectal cancer (CRC), primary ovarian insufficiency, and idiopathic recurrent pregnancy loss." (PMID 37905791, 2023).